CEBPA (CCAAT enhancer binding protein alpha)
Diseases named in the same sentence as CEBPA in open-access papers (continued):
Sharing a sentence is not in itself a finding about the gene and the disease.
cancer (continued). "CEBPA mRNA and protein have been reported in various cancer diseases." (PMID 35284484, 2022). "Interestingly, negative regulators of enhancer-associated genes including the TFs CEBPA, IRF8, IRF1 and ETV6, can suppress cancer cell growths." (PMID 31665430, 2020). "CEBPA has been reported as a tumor suppressor protein in various cancers, including HNSCC." (PMID 31053176, 2019). "For example, increased expression of oncogenic transcription factors such as MAF and CEBPA indicate miRNAs may regulate large networks of genes involved in cancer formation." (PMID 23741392, 2013). "As DNMT3B is mediating de novo DNA methylation and thus epigenetically inactivates tumour suppressor genes in cancer, these observations connect blocked differentiation through CEBPA suppression with deregulated methylation because of the suppressed miR-29b activity." (PMID 20628397, 2010). "Importantly, our conclusions only apply to AML, as CEBPA is not frequently mutated in other cancer types." (PMID 40221437, 2025). "Similarly, in a Cancer and Leukemia Group B study, which included 196 adult AML patients from two clinical studies, WT1 mutation predicted a worse 3-year disease-free and OS compared to wild-type WT1 AML patients independently of CEBPA, FLT3-ITD, and NPM1 mutational status." (PMID 41102401, 2026). "The analysis showed that TWIST1, RUNX1, CEBPA, and RELA were upregulated in carcinoma samples compared with normal renal tissues, whereas HIF1A was downregulated." (PMID 38724670, 2024). "In this study, we show that CRED9 positively regulates CEBPA expression and that expression of CRED9 differs among cancer cell lines." (PMID 34039742, 2021). "We further analyzed pathways of the predicted five cancer driver genes and found that KIT, ERBB2 and CEBPA are related to PI3K and RAS pathways." (PMID 32039169, 2019). "This shows that genes containing conserved RELA, STATI, IRFI, NF-kappaB, PEND, HLF, REL, CEBPA, DI_2, and NFKB1 binding sites are indeed over-represented in cancer-related DEGs and this over-representation can be recuperated computationally." (PMID 29593668, 2018). "Among the 16 cross-racial DRGs, all are cancer related according to ICGC and three genes (GATA3, SOX9 and CEBPA) have been regarded as cancer driver genes." (PMID 29745833, 2018). "Among the top 10 DRGs identified from TCGA-STAD dataset, six are GC related (E2F1, AK1B10, CEBPA, PTK7, RASAL1, GKN), and three are cancer related (DPCR1, GGT6, RAB25)." (PMID 29745833, 2018). "It is mostly expressed in epithelial tissues and has been shown to activate the protein kinase cascade that targets CCAAT/enhancer-binding protein alpha (CEBPA), following the same expression as PRKCH in both cancer cell lines." (PMID 25077705, 2014). "Furthermore, FTO can stabilize mRNA transcripts of MYC and CCAAT enhancer binding protein alpha (CEBPA), increasing the proliferation and survival of cancer cells." (PMID 40483535, 2025). "Taken together, these results indicate that cancer cell-derived exosomal miR-425-3p inhibits preadipocyte proliferation and differentiation through targeting related regulating genes such as GATA2, IGFBP4, MMP15, and CEBPA." (PMID 35941833, 2022).
cancer (continued). "Previous studies reported that RNA m6A methylation could affect various biological processes and signaling pathways, such as self-renewal and tumorigenesis of cancer stem cells, RNA metabolism, the FTO/m6A/MYC/CEBPA signaling, and the IL-7/STAT5/SOCS pathways." (PMID 32419773, 2020). "The mRNA and protein levels of CCAAT/enhancer binding protein alpha (CEBPA), known to be a transcription factor regulating cell differentiation and a target for degradation by TRIB2, as well as selected cancer stem cell makers in the Cisplatin-resistant cells, were measured." (PMID 29312632, 2017). "Among them were CEBPA and CEBPB (cell cycle regulation), RELA and CREL (NF-κB pathway), TCF7L1 (Wnt/β-catenin signaling pathway), SMAD3 [transforming growth factor beta (TGF-β) signaling], FOXO1 and NFAT, all of which are involved in cancer initiation and progression." (PMID 28344555, 2017). "We found that CEBPA protein levels could be upregulated by knocking down the overexpressed TRIB2, which also reversed the Cisplatin-resistance of these cells; further, the Cisplatin-resistant SCLC cells demonstrated certain cancer stem cell-like properties." (PMID 29312632, 2017).
infection (25 papers, 2010 to 2025). The state of being infected such as from the introduction of a foreign agent such as serum, vaccine, antigenic substance or organism. "ART-treated infection impacted the metabolic fraction (with elevated expression of PPARγ and CEBPα), the extracellular matrix (with elevated expression of COL1A2 and HIF-1α), and the inflammatory profile." (PMID 36231066, 2022). "Furthermore, within the transcription factor-gene network, SPI1 is closely related to NCF4 and CEBPA, both of which have a role in macrophage activation and infection response." (PMID 40677917, 2025). "Furthermore, the expression of HBcAg and known infection-promoting factors including glypican 5 (GPC5), peroxisome proliferator–activated receptor alpha (PPARA), and CCAAT/enhancer-binding protein alpha (CEBPA) was detected." (PMID 34631680, 2021). "In addition, we found that the protein expression level of CEBPα is significantly up-regulated 14 days post-infection and 21 days post-infection, while the CEBPβ expression level did not significantly change." (PMID 36747241, 2023).
metabolic disease (11 papers, 2013 to 2025). A congenital disorder (due to inherited enzyme abnormality) or acquired (due to failure of a metabolically important organ) disorder resulting from an abnormal metabolic process. "Based on the pseudo-temporal continuum profile, we identified the TF (ALX4, HINFP, CEBPA, CEBPB, DMBX1, MLXIPL, ONECUT1, and RBPJL) and depicted the regulated kernel genes co-networks, which were subjected to the metabolism disorders." (PMID 33462196, 2021). "We tested this approach with metabolic disease genes expressed in adipocytes, identifying and subsequently validating novel interactions between BSCL2 and PLIN1 (protein–protein) as well as CEBPA and AGPAT2 (genetic regulatory)." (PMID 30940487, 2019).
hematologic malignancies (7 papers, 2018 to 2024). "CEBPA is an important TF controlling hematopoietic differentiation and homeostasis, gene mutation and aberrant expression, which may contribute to hematological system diseases." (PMID 29357938, 2018). "The similarity of germline CEBPA, DDX41 and RUNX1 mutations associated with haematological diseases warrants further study, such as the long time to follow-up with the family members." (PMID 35279121, 2022). "Numerous studies support the complementary role of CEBPA and c-MYC transcription factors in risk stratification of hematologic malignancies development." (PMID 33170359, 2020). "Intriguingly, in comparison to the previous analysis, we observed 6 new non-synonymous SNVs linked to hematological disease, including variations in CBL (1 pt); DNMT3A (3 pts); FLT3 (1 pts), NQO1 (1 pt); NRAS (1 pts) and 2 frameshifts: CEBPA (1 pts) and NBN (1 pts)." (PMID 38612443, 2024). "CEBPA and c-MYC genes belong to TF and play an essential role in hematologic malignancies development." (PMID 33170359, 2020).
hematological tumors (1 paper, 2024). "The presence of germline mutations in DDX41 or CEBPA could inform clinicians about the relative risks of developing hematological tumors, the possible age at onset and the prognosis of the possible disease." (PMID 39118233, 2024).
CEBPA also shares sentences with these, for which no sentence is quoted: dyslipidemia (11 papers); Hyperglycemia (11); Hypoglycemia (11); acute lymphoblastic leukemia (7); Alzheimer disease (5); bone marrow failure syndrome (5); Cirrhosis (5); adenocarcinoma (4); Cachexia (4); esophageal cancer (4); hyperlipidemia (4); lipid metabolism disorders (4); lung diseases (4); lymphoma (4); non-alcoholic fatty liver disease (4); skin cancer (4); squamous cell carcinoma (4); bacterial infection (3); cardiovascular disease (3); colitis (3); head and neck cancer (3); idiopathic pulmonary fibrosis (3); lymphedema (3); prion disease (3); renal fibrosis (3); acute megakaryoblastic leukemia (2); adenoma (2); Arthritis (2); B-cell acute lymphoblastic leukemia (2); B-cell chronic lymphocytic leukemia (2).
A further 134 diseases each share a sentence with CEBPA in 2 papers or fewer.